ZDHHC17 (zDHHC palmitoyltransferase 17)
Description:
Palmitoyltransferase that catalyzes the addition of palmitate onto various protein substrates and is involved in a variety of cellular processes. Has no stringent fatty acid selectivity and in addition to palmitate can also transfer onto target proteins myristate from tetradecanoyl-CoA and stearate from octadecanoyl-CoA (By similarity). Palmitoyltransferase specific for a subset of neuronal proteins, including SNAP25, DLG4/PSD95, GAD2, SYT1 and HTT. Also palmitoylates neuronal protein GPM6A as well as SPRED1 and SPRED3. Could also play a role in axonogenesis through the regulation of NTRK1 and the downstream ERK1/ERK2 signaling cascade (By similarity). May be involved in the sorting or targeting of critical proteins involved in the initiating events of endocytosis at the plasma membrane. May play a role in Mg(2+) transport. Could also palmitoylate DNAJC5 and regulate its localization to the Golgi membrane (By similarity). Palmitoylates CASP6, thereby preventing its dimerization and subsequent activation.
Synonyms: DHHC17; HIP14; HIP3; HYPH; KIAA0946; HSPC294; DHHC-17
Tractability: Small molecule: a structure with a bound ligand is known; it has a high-quality binding pocket. Antibody: UniProt places it where antibodies can reach, with high confidence; UniProt predicts a signal peptide or a membrane-spanning region; its Gene Ontology location is reachable by antibodies, with medium confidence. PROTAC: ubiquitination databases record sites on it; its protein half-life has been measured.
Gene: Protein-coding gene on chromosome 12 (76,764,103 to 76,853,696, forward strand). Ensembl gene ENSG00000186908.
Subcellular location: Golgi apparatus membrane; Cytoplasmic vesicle membrane; Presynaptic cell membrane
Subcellular location (Human Protein Atlas): Golgi apparatus; Vesicles
Gene Ontology:
Molecular function: identical protein binding; palmitoyltransferase activity; protein binding; protein-cysteine S-palmitoyltransferase activity; protein-cysteine S-myristoyltransferase activity; protein-cysteine S-stearoyltransferase activity; signaling receptor binding
Biological process: lipoprotein transport; positive regulation of canonical NF-kappaB signal transduction; protein palmitoylation; regulation of programmed cell death; axonogenesis; regulation of ERK1 and ERK2 cascade; regulation of neurotrophin TRK receptor signaling pathway; regulation of modification of synapse structure, modulating synaptic transmission
Cellular component: cytoplasmic vesicle membrane; Golgi apparatus; Golgi membrane; Golgi-associated vesicle membrane; presynaptic membrane; glutamatergic synapse; perforant pathway to dendrate granule cell synapse; postsynaptic Golgi apparatus
Genetic constraint (gnomAD): Loss-of-function variants: 26 observed, 55.64 expected, observed/expected ratio (o/e) 0.47, 90% interval 0.34 to 0.65. The upper end of that interval is the gene's LOEUF score, 0.65, which puts it in group 2 of 6, group 1 being the genes least tolerant of losing a copy. Missense variants: 497 observed, 561.39 expected, observed/expected ratio (o/e) 0.89, 90% interval 0.82 to 0.95. Synonymous variants: 186 observed, 177.45 expected, observed/expected ratio (o/e) 1.05, 90% interval 0.93 to 1.18.
Homologues: Orthologues: chimpanzee ZDHHC17 (100% identical), macaque ZDHHC17 (100% identical), rabbit ZDHHC17 (99% identical), dog ZDHHC17 (99% identical), rat Zdhhc17 (99% identical), mouse Zdhhc17 (99% identical), guinea pig ZDHHC17 (95% identical), pig ZDHHC17 (92% identical), tropical clawed frog zdhhc17 (89% identical), zebrafish zdhhc17 (88% identical), Drosophila melanogaster Hip14 (46% identical). Paralogues in human: ZDHHC13 (47% identical), ANKRD35 (16% identical).
Diseases named in the same sentence as ZDHHC17 in open-access papers:
ZDHHC17 is named in the same sentence as 31 diseases in open-access papers, as found by Europe PMC text mining. Sharing a sentence is not in itself a finding about the gene and the disease. The quoted sentences say what the papers report.
Huntington disease (12 papers, 2012 to 2025). Huntington disease (HD) is a rare neurodegenerative disorder of the central nervous system characterized by unwanted choreatic movements, behavioral and psychiatric disturbances and dementia. "Several of these have been associated with other neurodegenerative disorders (ZDHHC17 with Huntington’s disease, SYT11 and GAK with Parkinson’s disease and GABRB3 with dementia with Lewy bodies), and may be of special interest for future studies." (PMID 34202490, 2021). "The key marker for Huntington disease (HD), huntingtin (htt), is normally palmitoylated at Cys214 by huntingtin interacting protein 14 (HIP14), a palmitoyltransferase also known as ZDHHC17." (PMID 33430908, 2021). "In light of the connection between the tip1 mutation and autoimmunity in Arabidopsis, it would be interesting for future research to examine whether mutations in zDHHC17 or other TIP1 orthologues are associated with dysbiosis and/or whether dysbiosis is involved in Huntington’s disease development." (PMID 39242981, 2024). "Given the role of NMNAT2 in axon survival, the finding that zDHHC17 could regulate NMNAT2 palmitoylation suggests a potential impairment of NMNAT2 palmitoylation and subcellular targeting in Huntington disease models that warrants further investigation." (PMID 25271157, 2014).
glioma (7 papers, 2019 to 2024). A benign or malignant brain and spinal cord tumor that arises from glial cells (astrocytes, oligodendrocytes, ependymal cells). "In addition, the gene encoding ZDHHC17 is located in the chromosomal region containing a potential oncogene of glioma." (PMID 33541421, 2021). "zDHHC17 is also aberrantly expressed in gliomas, and it has been determined that the zDHHC17/MAPK signaling module is essential for promoting radiotherapy resistance in gliomas." (PMID 38293675, 2023). "Both western blotting and RT-PCR results indicated that MAP2K4 and ZDHHC17 were increased in the glioma spheres after 6 Gy radiation or TMZ treatment, similar to EZH2 expression." (PMID 31938047, 2020). "Overall, the present study showed that ZDHHC17 was up-regulated in glioma as compared to normal brain tissue, and that it recruited MAP2K4 and JNK/p38 to build a signaling module for JNK/p38 activation in GBM." (PMID 31938047, 2020). "Although ZDHHC17 and MAP2K4 staining intensities varied among the untreated glioma tissues, ZDHHC17 and MAP2K4 expression tended to increase in recurrent compared to naive tumor sections (4 of 5)." (PMID 31938047, 2020). "ZDHHC17 and MAP2K4 expression was markedly enhanced in mesenchymal GSCs, which are closely associated with post-radiation or chemotherapeutic glioma recurrence." (PMID 31938047, 2020). "The role of ZDHHC17 in glioma growth was also evaluated using a tumor formation assay." (PMID 31938047, 2020). "However, other ZDHHCs, such as ZDHHC17, have been found to accelerate glioma progression by interacting with MAP2K4, and this function may depend on the ZDHHC17 ankyrin-repeat domain, rather than its palmitoyltransferase activity." (PMID 37161425, 2023). "Moreover, the gene encoding ZDHHC17 is located in the chromosomal region containing a potential oncogene for glioma and ZDHHC17 protein can interact with MAP2K4 to regulate the development and progression of malignant glioma and stimulate JNK/p38 (our unpublished data)." (PMID 30658672, 2019). "It has been determined that genistein can inhibit the zDHHC17/MAPK signaling module, thus reducing radiotherapy resistance in gliomas." (PMID 38293675, 2023). "It was found that ZDHHC5, ZDHHC17, ZDHHC18, and ZDHHC23 promote cellular self‐renewal by targeting glioma stem cells, which in turn induces malignant progression of tumor cells." (PMID 37434393, 2023). "Expression of both ZDHHC17 and MAP2K4 was progressively elevated in glioma samples from grade I to grade IV versus normal brain tissues, and was highly correlated." (PMID 31938047, 2020). "Next, we checked ZDHHC17 and MAP2K4 expression in a glioma tissue microarray (TMA) by immunohistochemistry." (PMID 31938047, 2020). "Our results indicated that ZDHHC17 recruits JNK/p38 and MAP2K4 to form a signaling module for JNK/p38 activation during glioma progression and malignant development." (PMID 31938047, 2020). "Importantly, the JNK/p38 activation promoted by ZDHHC17 is independent of PAT, and glioma cells with suppressed ZDHHC17 expression are insensitive to 2-BP inhibition." (PMID 39563863, 2024). "Nevertheless, a critical role of ZDHHC17 in glioma growth and progression is not known." (PMID 31938047, 2020). "ZDHHC17 over-expression could help maintain glioma cell stemness because the upregulation of the SOX2-positive cell population, whereas MAP2K4 knockdown or genistein treatment suppressed glioma stem cell (GSC) self-renewal." (PMID 31938047, 2020).
glioma (continued). "Attesting to its specificity, the expression of ZDHHC13, the homeodomain protein of ZDHHC17, was not related to MAP2K4 expression in glioma tissue." (PMID 31938047, 2020). "Notably, ZDHHC17-promoted activation of JNK/p38 was PAT-independent, and ZDHHC17-expressing glioma cell malignancy characteristics were not suppressed by the PAT inhibitor, 2-bromopalmitate (2BP)." (PMID 31938047, 2020).
glioblastoma (3 papers, 2020 to 2025). The most malignant astrocytic tumor (WHO grade IV). "Another study found that OCT4A was a substrate of ZDHHC17, and its palmitoylation is indispensable for preserving it from lysosome degradation and enhancing stemness in glioblastoma." (PMID 40814339, 2025). "It was reported that ZDHHC17 was upregulated in glioblastoma multiforme (GBM) and contributed to GBM malignant development through promoting MAP2K4 and P38/JNK activation." (PMID 35297315, 2022). "To characterize inhibitor efficacy, we also investigated 20 inhibitors using different ZDHHC17-positive patient-derived glioblastoma sphere samples, finding that 12 exhibited therapeutic effects." (PMID 31938047, 2020).
breast cancer (2 papers, 2016 to 2019). A primary or metastatic malignant neoplasm involving the breast. "The SLAIN2 FS was present in the 4T1 mammary cancer cell line, but ZDHHC17 FS was not." (PMID 31578439, 2019).
colon cancer (2 papers, 2022 to 2025). "In addition, the expression of ZDHHC17 (also known as HIP14) is upregulated in breast and colon cancer." (PMID 36359005, 2022).
malignant glioma (2 papers, 2019 to 2021). A grade III or grade IV glioma arising from the central nervous system. "ZDHHC17 protein can interact with MAP 2K4 to regulate the development and progression of malignant glioma and stimulate JNK/p38." (PMID 33541421, 2021).
brain tumour (1 paper, 2025). "ZDHHC17, known for its role in neuronal protein trafficking, might similarly influence CD47 localization in neuroinflammatory or brain tumour microenvironments." (PMID 41163221, 2025).
ductal carcinoma (1 paper, 2011). "Mcs6 human orthologous transcripts that have been reported as differentially expressed between non-diseased breast tissue and ductal carcinoma tissue encode for two phosphatases (DUSP6, PPP1R12A), a proteoglycan (EPYC), a redox regulator (TXNRD1), and two uncharacterized proteins (ALX1, ZDHHC17)." (PMID 21625632, 2011).
hepatocellular carcinoma (1 paper, 2025). A malignant tumor that arises from hepatocytes. "For example, a 2024 study in hepatocellular carcinoma showed that the palmitoyltransferases ZDHHC17 and ZDHHC24 can palmitoylate AKT, anchoring it to the plasma membrane and significantly increasing AKT kinase activity." (PMID 40740766, 2025).
ischemic stroke (1 paper, 2023). A stroke disorder caused by obstruction of blood flow to the brain, due to thrombotic (local blood clot formation) or embolic (due to a blood clot or other material traveling from another site) event. "zDHHC17 interacts with c-Jun N terminus kinase (JNK) to activate JNK and promote neuronal cell death in response to pathophysiological triggers like ischemic stroke." (PMID 37064897, 2023).
melanoma (1 paper, 2025). A malignant, usually aggressive tumor composed of atypical, neoplastic melanocytes. "Silencing ZDHHC17 or ZDHHC21, however, had no significant impact on CTNND1 palmitoylation or melanoma cell invasion." (PMID 41321310, 2025).
vulva cancer (1 paper, 2020). A primary or metastatic malignant neoplasm involving the vulva. "ZDHHC17 is up-regulated in stomach, colon, brain, and lung tumors concordant with tumor stage gradation 33, 34, but down-regulated in liver, pancreas, thyroid gland, and vulva cancers." (PMID 31938047, 2020).
cancer (7 papers, 2010 to 2026). A tumor composed of atypical neoplastic, often pleomorphic cells that invade other tissues. "Clinically, high ZDHHC17 expression is positively correlated with non-response to anti-PD-1 therapies in cancer patients, partially due to CDK4-mediated repression of PD-L1." (PMID 42133178, 2026). "In sum, our study uncovers a novel cell cycle control mechanism by ZDHHC17-mediated palmitoylation and TRAF6-mediated ubiquitination of CDK4, presenting a potential therapeutic avenue by targeting the ZDHHC17-TRAF6-CDK4 axis for cell cycle dysregulated cancers." (PMID 42133178, 2026). "Although the cancer cells did not grow differently in culture, tumors carrying the fusion grew significantly faster than controls upon grafting on mice, suggesting that the ZDHHC17-LNCKB.11978 fusion does indeed have oncogenic activity." (PMID 37638762, 2023).
tumor (7 papers, 2019 to 2025). "Similarly, MAP2K4- or ZDHHC17- positive tumor cells or proportions were raised overall in recurrent compared with matched primary tumors." (PMID 31938047, 2020). "ZDHHC17-expressing GSCs could efficiently develop and form intracranial tumors in vivo, whereas ZDHHC17 depletion clearly suppressed tumor growth." (PMID 31938047, 2020). "However, the same ZDHHC gene may be amplified in some tumor types but deleted in others (e.g. ZDHHC17, ZDHHC20, and ZDHHC21)." (PMID 31938047, 2020). "ZDHHC17 and ZDHHC20 may act as oncoproteins 43, 44, but ZDHHC2 and ZDHHC13 can act as tumor suppressors 45-47." (PMID 32863941, 2020). "When tested as gene vaccines in the mouse tumor injection model of 4T1, SLAIN2-FS conferred tumor retardation but ZDHHC17 did not." (PMID 31578439, 2019). "Upon engrafting mice, both mut-ZDHHC17-LNCKB.11978 and RPSAP52-LNCKB.11978 promoted in vivo tumor growth, although not reaching statistical significance due to large variations in animal experiments." (PMID 37638762, 2023).
neurological disease (4 papers, 2016 to 2025). "We found an interaction between Us9 and Zdhhc17, a palmitoyltransferase of the SNARE protein Snap25, implicated in the regulation of neuronal vesicle-trafficking and associated with neurological diseases such as Huntington’s." (PMID 33370419, 2020).
infection (2 papers, 2021 to 2024). The state of being infected such as from the introduction of a foreign agent such as serum, vaccine, antigenic substance or organism. "We first knocked down the palmitoylation enzyme zDHHC17 in MDA-MB231 cells by using lentiviral infection with several shRNA constructs." (PMID 38876303, 2024). "ZDHHC17 affects viral genome replication during the SADS-CoV infection cycle." (PMID 34700373, 2021).
ZDHHC17 also shares sentences with these, for which no sentence is quoted: mental disorder (2 papers); Alzheimer disease (1); Anxiety (1); Ataxia (1); bacterial infection (1); bipolar disorder (1); dementia (1); depression (1); neurodegenerative disease (1); Parkinson disease (1); prostate carcinoma (1); schizophrenia (1); Sepsis (1); testicular germ cell tumor (1); X-linked intellectual disability (1).